IL5 (interleukin 5)
Diseases named in the same sentence as IL5 in open-access papers (continued):
Sharing a sentence is not in itself a finding about the gene and the disease.
bladder tumor (2 papers, 2012 to 2023). "Thus, increases in IL-5 levels in this study might be responsible for augmented development of bladder tumor cells and their inability to be recognized by inflammatory." (PMID 22962576, 2012). "Targeting ILC2s by blocking IL-4/IL-13 signaling pathways, IL-5, or IL-33 receptor, or using IL-33-deficient or ILC2-deficient mice, did not affect mice survival following bladder tumor implantation." (PMID 38283350, 2023). "However, the absence of ILC2s in these mice did not affect the mice survival following bladder tumor challenge, in line with the results obtained when blocking IL-4/IL-13 or IL-5 signaling pathways, or IL-33/ST2 axis." (PMID 38283350, 2023).
calculus (2 papers, 2024 to 2025). "Urolithiasis also impacts the expression of cytokines such as IL-2, CTACK, IL-5, IL-7, IL-8, GRO-α, MIG, and MIP-1α." (PMID 39021826, 2024).
capillary leak syndrome (2 papers, 2021 to 2025). A syndrome characterized by leakage of intravascular fluids into the extravascular space. "The pathogenesis of eosinophilic serositis, manifested as pleural and pericardial effusions, is a result of IL-5 and eotaxin-induced chemotaxis leading to capillary leak syndrome and tissue invasion." (PMID 40926948, 2025). "IL-2-induced capillary leak syndrome presents high levels of both IL-5 and eosinophils." (PMID 33916211, 2021).
cardiac hypertrophy (2 papers, 2023 to 2024). "IL‐5 deficiency promoted the development of cardiac hypertrophy, exacerbated the degree of cardiac fibrosis and further worsened cardiac dysfunction in Ang II‐infused mice." (PMID 38963241, 2024). "The results showed that IL‐5 deficiency significantly increased the mRNA expression of cardiac hypertrophy markers, such as ANP, BNP and β‐MHC." (PMID 38963241, 2024). "IL‐5 knockout significantly increased the Ang II‐induced mRNA expression of cardiac hypertrophy markers in myocardial cells that were co‐cultured with macrophages, and this effect was reversed by S31‐201." (PMID 38963241, 2024). "We found knockout of IL‐5 significantly increased the expression of cardiac hypertrophy markers, elevated myocardial cell cross‐sectional areas and worsened cardiac dysfunction in Ang II‐infused mice." (PMID 38963241, 2024). "Finally, the effects of IL‐5 on macrophage differentiation and macrophage‐related cardiac hypertrophy and fibrosis were analysed in vitro." (PMID 38963241, 2024).
cataract (2 papers, 2020 to 2023). Partial or complete opacity of the crystalline lens of one or both eyes that decreases visual acuity and eventually results in blindness. "The level of IL-12p40, MIP-1d, IL-7, IL-6R, BLC, TNF-a, IL-5 were elevated in the SG samples compared to the samples of the cataract patients." (PMID 32117217, 2020).
Cerebral ischemia (2 papers, 2019 to 2023). Restriction of arterial blood supply to the brain associated with insufficient oxygenation to support the metabolic requirements of the tissue. "Therefore, the regulation of IL-4 or IL-5 and its associated pathways are potential targets for the treatment of cerebral ischemia." (PMID 31164999, 2019).
chlamydia (2 papers, 2009). "Elevated levels of IL-4 and IL-5 in splenic lymphocytes from IFN-γ--/-- mice following chlamydia-specific challenge and the inability in controlling local chlamydial infection and associated tissue damage and cellular infiltration has also been reported." (PMID 19698128, 2009).
Chlamydia infections (2 papers, 2017 to 2025). "Conversely, our findings reveal that CCR2 deficiency leads to excessive Th2-type immune responses, characterized by increased production of IL-4 and IL-5, which compromise the host’s ability to effectively combat intracellular Chlamydia infections." (PMID 39903705, 2025). "In addition to the significant increase in IL-5 would lead to increased Th2 response which is not protective during chlamydia infection." (PMID 29216217, 2017).
cholangitis (2 papers, 2024 to 2025). An acute or chronic inflammatory process affecting the biliary tract. "Zen research showed that the expression of Th2 cytokines (IL-4, IL-5, and IL-13) and regulatory cytokines (IL-10 and transforming growth factor-β) was upregulated in the lesion tissues of patients with IgG4-related sclerosing pancreatitis and cholangitis." (PMID 38669380, 2024).
chronic heart failure (2 papers, 2011 to 2025). "After weighting, anti-IL5/IL5R therapy was associated with a significantly lower risk of congestive heart failure (aHR 0.63, 95% CI 0.52–0.76), arrythmia (aHR 0.78, 95% CI 0.68–0.90), and peripheral artery disease (aHR 0.69, 95% CI 0.54–0.87) compared with non-biologic users." (PMID 40823190, 2025). "It is worth noting that our study, for the first time, has associated IL-5, IL-7, IL-9, and IFN-γ plasma levels with chronic heart failure." (PMID 21418620, 2011). "Anti-IL5/IL5R use was associated with a significantly lower risk of mortality (aHR 0.35, 95% CI 0.29–0.42), congestive heart failure (aHR 0.63, 95% CI 0.52–0.76), arrythmia (aHR 0.78, 95% CI 0.68–0.90), and peripheral artery disease (aHR 0.69, 95% CI 0.54–0.87) compared with non-biologic users." (PMID 40823190, 2025). "Further studies are needed to assess whether the modification of IL-5, IL-7, IL-9 and IFN-γ plasma levels has a null, a protective, or a pathogenetic role in chronic heart failure and may constitute a potential target for therapeutic intervention." (PMID 21418620, 2011). "However, what was noteworthy, and described here for the first time, was the increase of IL-9, and decrease of IL-5, IL-7 and IFN-γ plasma levels in patients with chronic heart failure." (PMID 21418620, 2011). "Furthermore, a statistically significant correlation with IL-5 plasma levels was found only among NYHA III/IV ICM patients, but not among patients with less severe chronic heart failure." (PMID 21418620, 2011).
corneal disease (2 papers, 2021 to 2023). "In this study, we evaluated the cytokine profiles of IL-2, IFN-γ, ICAM-1, IL-5, IL-6, IL-8, IL-10, IL-1β, MCP-1, IL-17A, IP-10, G-CSF, and VEGF-A in the AqH of BK patients before and after DMEK and in a control group without corneal disease." (PMID 34426617, 2021).
cysticercosis (2 papers, 2023 to 2024). "Positive cysticercosis status was significantly associated with a decrease in IL-10 levels (β = -0.419, p = 0.022), while IL-5 levels were significantly increased (β = 0.229, p = 0.035)." (PMID 39093864, 2024). "Our study found no significant changes in the overall cytokine profiles between HIV+ and HIV- participants coinfected CC and NCC, except for IL-5 which was elevated in HIV+ individuals with cysticercosis." (PMID 39093864, 2024). "Our findings suggest that coinfection with HIV and neurocysticercosis (NCC) does not significantly modulate peripheral cytokine profiles, despite the elevated IL-5 levels observed in HIV-positive individuals with cysticercosis." (PMID 39093864, 2024). "In addition, it is known that IL-5 and IL-6 participate in the recruitment of eosinophils, which are considered important effectors in the destruction of parasites in porcine cysticercosis." (PMID 37242348, 2023). "However, contrary to initial hypotheses, the coexistence of HIV with cysticercosis did not lead to significant alterations in the levels of TNF-α, IFN-γ, IL-5, and VCAM-1." (PMID 39093864, 2024).
delayed hypersensitivity reactions (2 papers, 2023 to 2025). "A type IV hypersensitivity reaction, Th2-mediated and driven by interleukin-4 (IL-4), IL-5 and IL-13, promoting IgE production by B cells and activating eosinophils and mast cells, has been suggested." (PMID 40371306, 2025).
delirium (2 papers, 2016 to 2025). A disorder characterized by confusion; inattentiveness; disorientation; illusions; hallucinations; agitation; and in some instances autonomic nervous system overactivity. "For IL-5, there was a statistically significant increase in the POCD/delirium group at 18 h after surgery compared to baseline (p = 0.0333)." (PMID 27577265, 2016).
diabetic retinopathy (2 papers, 2024 to 2025). "Noticeably, despite the absence of diabetic retinopathy, IL-5, G-CSF, and CCL11/eotaxin-1 concentrations demonstrated a significant inverse correlation with MCV and MMT." (PMID 39201047, 2024).
diphtheria (2 papers, 2013 to 2016). A Gram-positive bacterial infection caused by Corynebacterium diphtheriae. "In a previously published study on elderly adults we found a weak correlation between IL-5-producing T cells measured by Elispot and diphtheria-specific Abs." (PMID 27602049, 2016). "Our cohort thus partly seemed to have a too small diphtheria-specific memory B cell pool and T cell help was only borderline detectable in the form of low IL-5 production during the response." (PMID 24349407, 2013).
endothelial dysfunction (2 papers, 2020 to 2021). In vascular diseases, endothelial dysfunction is a systemic pathological state of the endothelium (the inner lining of blood vessels) and can be broadly defined as an imbalance between vasodilating and vasoconstricting substances produced by (or acting on) the endothelium. "For instance, pro-inflammatory metabolites (such as NO-related molecules), cytokines (including IL-1β, TNF-α, IFN-γ, IL-4, IL-5, IL-8, G-CSF, and MIP-1b), and markers of endothelial dysfunction (e.g., homocysteine) were found to be increased in VaD patients." (PMID 32340195, 2020).
eosinophilic bronchiectasis (2 papers, 2023 to 2025). A bronchiectasis inflammatory endotype characterized by elevated blood eosinophils (≥300 cells/μL) or sputum eosinophils (≥3%), associated with type 2 (Th2) inflammation, elevated fractional exhaled nitric oxide (FeNO), and IL-5/IL-13 signaling. "In summary, our cross-sectional molecular analyses support the notion of eosinophilic bronchiectasis as predominantly IL-5 driven; however, our statistical power is weak and our findings should be interpreted accordingly." (PMID 37780108, 2023). "So far, the effectiveness of anti-IL-5 or anti-IL-5 receptor monoclonal antibodies in severe eosinophilic bronchiectasis has been documented in a case series, which demonstrated marked improvements in exacerbation rates and lung function after six months of treatment." (PMID 40589741, 2025).
Fever (2 papers, 2019 to 2024). Body temperature elevated above the normal range. "However, post-marketing reports and product inserts for mepolizumab and benralizumab revealed indications of pyrexia, suggesting a potential association between these anti-IL-5 drugs and pyrexia." (PMID 38308249, 2024). "The role of anti-IL-5 drugs in the genesis of pyrexia remains ambiguous." (PMID 38308249, 2024). "All in all, the present study has identified IFN-α as a universal biomarker of human OROV fever, while CXCL8 & IL-5 and CXCL10 & IL-17 were observed consistently in early and late seroconverters, respectively." (PMID 31784575, 2019).
graft-v-host disease (2 papers, 2022 to 2023). "Enhanced Treg production following IUT, particularly of CD62L+ CD25+ FOXP3+ Tregs, protects against graft-v-host disease, and together with putative Breg (expressing IL10, IL5, IL6, FOXP3, TGF-β), probably influenced the resulting tolerogenic or immunogenic responses." (PMID 37226255, 2023). "MLCK; myosin light chain kinase, PAMPs; pathogen-associated molecular patterns, LPS; lipopolysaccharide, DAMPs; damage-associated molecular patterns, APC; antigen-presenting cell, IFN-γ; interferon gamma, TNF-α; tumor necrosis factor alpha, IL-5; interleukin 5, GVHD; graft-versus-host disease." (PMID 36555600, 2022).
Hashimoto thyroiditis (2 papers, 2017 to 2022). An autoimmune disorder caused by the production of autoantibodies against thyroid tissue. "In addition, similar conclusions regarding the IL5 rs2069812 polymorphism concern also such diseases as Hashimoto’s thyroiditis or bronchial asthma." (PMID 36361964, 2022).
Hepatic steatosis (2 papers, 2016 to 2024). Steatosis is a term used to denote lipid accumulation within hepatocytes. "Results: the HFHS diet induced, in the dams, hepatic steatosis, oxidative stress (reduced catalase, elevated protein oxidation) and the activation of pro-inflammatory pathways (p38-MAPK), along with imbalanced circulating cytokine concentrations (increased IL-6 and decreased IL-5 and IL-17A)." (PMID 38671859, 2024).
hepatitis B (2 papers, 2016 to 2024). "In light of this finding, we evaluated IFN-γ, IL-5, and or IL-10 production in whole blood cultures in response to HbsAg stimulation before and after hepatitis B immunization and also analyzed if cytokine production was associated with antibody responses to the immunizations." (PMID 27926921, 2016). "Furthermore, we found that IL-5 and HGF were promising predictors for predicting the immunization response to hepatitis B vaccine in infants, and the combination of the two cytokines showed the best predictive efficiency, with an area under the curve (AUC) value of 0.844." (PMID 38495649, 2024).
Hyperglycemia (2 papers, 2020 to 2023). An increased concentration of glucose in the blood. "As expected, these changes in protein expression were found to be concordant with the transcriptional modulations in cultured macrophages which displayed upregulated gene expression of M1 (CD11c, TNF-α, and IL-1β) and downmodulated M2 (IL-5) markers under constant or fluctuating hyperglycemia." (PMID 32806763, 2020).
idiopathic pulmonary fibrosis (2 papers, 2021 to 2025). Idiopathic pulmonary fibrosis (IPF) is a nonneoplastic pulmonary disease that is characterized by the formation of scar tissue within the lungs in the absence of any known cause. "Another study has shown that in the treatment of idiopathic pulmonary fibrosis (IPF), increasing the content of IL-5 can reduce the mortality caused by ALI." (PMID 34057015, 2021). "By degrading the mRNA of transcription factors Gata3 and Egr1, it indirectly suppresses the production of pro-fibrotic cytokines such as IL-5 and IL-13, thereby limiting the progression of idiopathic pulmonary fibrosis (IPF)." (PMID 41154702, 2025).
ileitis (2 papers, 2013 to 2024). "Our results showed that the induction of ileitis was associated with the presence of both Th1- and Th2-type effector responses, since we observed increased secretion of IFNγ, as well as IL-4 and IL-5." (PMID 23977323, 2013). "The expansion of neutrophils in the BALF of SHIP-1−/− mice with ileitis coincided with a significant increase in the key neutrophil regulator G-CSF, while the expansion of eosinophils correlated with significant increases eosinophil regulators in BALF including eotaxin, IL-4 and IL-5." (PMID 39432107, 2024). "Other differences in circulating cytokines were also noted including increases in IL-5, CCL3 and CCL4 that were not seen in SHIP-1−/− without ileitis." (PMID 39432107, 2024).
kidney damage (2 papers, 2017 to 2025). "Less-characterized interleukins such as IL-3, IL-5, IL-9, and IL-27 demonstrate dual or context-dependent roles, particularly in shaping immune tolerance and tissue-specific complications such as nephropathy and neuropathy." (PMID 40804870, 2025). "While serum levels of IFN-γ, IL-2, IL-4, and IL-12 did not display a difference between experimental groups (data not shown), expression of IL-5, IL-6, TNF-α, IL-10, CXCL1, and IL-1β was elevated in the NZM2410/J mice displaying signs of severe kidney damage." (PMID 28491039, 2017).
kidney failure (2 papers, 2020 to 2021). An acute or chronic condition that is characterized by the inability of the kidneys to adequately filter the blood. "This complement pathway activation and positive bio-feedback loops involving interleukin-5 (IL-5) and tryptase are much more common than recognized involving patients who develop renal failure or fatal cerebral events." (PMID 33807579, 2021).
Listeria monocytogenes infection (2 papers, 2019). "During pregnancy in women, pregnancy-specific glycoprotein releases into blood circulation, promotes the development of IL-5-secreting cells to protect against Listeria monocytogenes infection, which is implicated in the successful pregnancy." (PMID 31100843, 2019).
measles (2 papers, 2020 to 2021). A highly contagious viral infection caused by the measles virus. "A Th1 cytokine profile, with elevations in peripheral blood gamma interferon (IFN-γ) and interleukin-2 (IL-2), is present during the measles prodrome, whereas measles convalescence is characterized by elevations in Th2 cytokines, such as interleukin-4 (IL-4) and interleukin-5 (IL-5)." (PMID 32085446, 2020).
microscopic polyangiitis (2 papers, 2021 to 2024). Microscopic polyangiitis (MPA) is an inflammatory, necrotizing, systemic vasculitis that affects predominantly small vessels (i.e. small arteries, arterioles, capillaries, venules) in multiple organs. "MPO/ANCA-positive EGPA has a significant association with HLA class II DQ haplotype, which is shared with the other MPO-AAV (i.e., microscopic polyangiitis, MPA), while ANCA-negativity is associated with GP33 and IL5/IRF1 loci, indicating a possible mucosal/barrier dysfunction origin." (PMID 33718405, 2021).
Miscarriage (2 papers, 2019 to 2021). A pregnancy that ends at a stage in which the fetus is incapable of surviving on its own, defined as the spontaneous loss of a fetus before the 22th week of pregnancy. "Weak positive correlations were found between Il-5 and the number of miscarriages (rho = 0.264, p = 0.0394)." (PMID 34444287, 2021). "We observed significantly higher levels of Il-4 and Il-5 (which belong to Th2 cytokines) in women with miscarriage." (PMID 34444287, 2021). "However, according to the literature, Il-5 reaches significantly lower serum levels in women with recurrent miscarriage than in women at the end of the normal first trimester and before delivery." (PMID 34444287, 2021). "They showed that the concentrations of Il-5 as well as Il-4 or TNF-β are undetectable in sera of both healthy pregnant women and those with recurrent miscarriage." (PMID 34444287, 2021).
mycosis fungoides (2 papers, 2024). Classical mycosis fungoides is the most common type of mycosis fungoides (MF), a form of cutaneous T-cell lymphoma, and is characterized by slow progression from patches to more infiltrated plaques and eventually to tumors. "Previous studies conducted in Mycosis fungoides and Sézary syndrome have shown that SATB1 can influence the expression of IL5 and IL9." (PMID 39195213, 2024).
nephritis (2 papers, 2022 to 2025). Inflammation of renal tissue. "In nephritis, a urine proteomic signature (IL‐5 + Fas) achieves an AUC of 0.94 for diagnosing ICIs‐associated acute interstitial nephritis, enabling noninvasive monitoring." (PMID 40787068, 2025).
ocular toxoplasmosis (2 papers, 2018 to 2020). Ocular toxoplasmosis is an infection in the eye caused by the parasite, Toxoplasm a gondii. "Upregulation of IL-5 has been related to severe clinical features of ocular toxoplasmosis with increased levels of IL-5 found in the aqueous humor samples of patients with acute and recurrent ocular toxoplasmosis." (PMID 33028847, 2020). "As for early prognosis T. gondii-specific IL5+CD4+ T-cells and IFN-γ produced by NK-cells displayed high accuracy to define respectively ocular involvement and acute/chronic phase of ocular toxoplasmosis in infants with congenital disease." (PMID 33028847, 2020).
Onchocerca volvulus infection (2 papers, 2012 to 2024). "The results obtained from these different studies suggest the important roles of both TNF-α and IL-5 in the generation of protective immunity against onchocerciasis." (PMID 39432476, 2024). "Although we could not confirm a negative correlation between the amount of MF and secreted levels of IL-5, as described for Onchocerca volvulus infection, we could show that microfilaremic individuals produced less IL-5 and that MF levels were correlated to the number of worm nests." (PMID 22509424, 2012).